MTAP (methylthioadenosine phosphorylase)
Diseases named in the same sentence as MTAP in open-access papers (continued):
Sharing a sentence is not in itself a finding about the gene and the disease.
lymph node metastasis (1 paper, 2025). "MTAP expression was significantly linked to pT stage (p = 0.0004), classical and quantitative Gleason grade (p < 0.0001 each), and presence of lymph node metastasis (p = 0.0315, but was unrelated to PSA recurrence (p > 0.1779)." (PMID 40554389, 2025).
melanocytic neoplasm (1 paper, 2026). "Recently, MTAP has emerged as a relevant biomarker in the context of melanocytic neoplasms due to its dual biological and diagnostic significance." (PMID 41596618, 2026). "In this dual-marker paradigm, MTAP not only refines the classification of diagnostically ambiguous melanocytic neoplasms but may also hold therapeutic implications, identifying tumors potentially susceptible to PRMT5 and related methyltransferase inhibitors in the context of 9p21 codeletion." (PMID 41596618, 2026).
periampullary cancers (1 paper, 2024). "In a study with pancreatic and periampullary cancers, in which CDKN2A HD is common (40%), it was reported that CDKN2A HD was seen in half of the cases without MTAP HD." (PMID 38109891, 2024).
peripheral T-cell lymphoma (1 paper, 2015). "We also showed that subsets of peripheral T-cell lymphoma lack MTAP in a high percent of cases." (PMID 25917288, 2015).
pilomyxoid astrocytoma (1 paper, 2018). An astrocytic tumor of uncertain relation to pilocytic astrocytoma. "However, in LGG74, identified as pilomyxoid astrocytoma BRAFwt, MTAP gene levels were slightly down-regulated." (PMID 30558563, 2018).
primary biliary cholangitis (1 paper, 2020). Primary biliary cholangitis (PBC) is a chronic and slowly progressive cholestatic liver disease of autoimmune etiology characterized by injury of the intrahepatic bile ducts that may eventually lead to liver failure. "Our results suggest that hsa-miR-23b is involved in pathophysiology of primary biliary cholangitis through interleukin-12 signaling via regulation of CNN2, JAK1, LMNB1, MTAP, SOD2, and TCP1." (PMID 33036164, 2020).
renal carcinoma (1 paper, 2022). A carcinoma arising from the epithelium of the renal parenchyma or the renal pelvis. "We previously uncovered that MTAP‐deficient renal carcinoma cells become addicted to IGF1R activity to drive oncogenic pathways, so the selective IGF1R inhibitor preferentially impairs their viability and invasiveness." (PMID 35766227, 2022).
Salmonella Infections (1 paper, 2018). Infections with bacteria of the genus SALMONELLA. "Based on these results and our demonstration that high extracellular MTA concentrations suppress virulence, we hypothesize that MTAP inhibitors could be a host-directed therapy during Salmonella infection." (PMID 29866910, 2018).
small cell carcinoma (1 paper, 2022). A neuroendocrine carcinoma composed of small malignant cells which are often said to resemble "oat cells" under the microscope. "The small cell carcinoma did not harbor any reportable mutations; BAP1 and mTAP expression were preserved in this tumor." (PMID 35565429, 2022).
superficial spreading melanoma (1 paper, 2016). A type of melanoma that typically occurs in light-skinned individuals ranging in age from young adults to the elderly. "Superficial spreading melanoma (SSM) and nodular melanoma (NM characteristically express the eight genes GALNT7, DIS3, FGFR1OP, G3BP2, MTAP, SEC23IP, USO1, and ZNF668." (PMID 27322213, 2016).
T cell deficiency (1 paper, 2025). "Despite the survival advantage that MTAP deletion confers to the OS TME through T cell deficiency, we identified a related metabolic vulnerability in DuNN shMtap tissues—activation of methionine metabolism, a pathway previously reported to be synthetically lethal with MTAP deletion." (PMID 39983717, 2025).
T-cell leukemia (1 paper, 2025). A malignant disease of the T-lymphocytes in the bone marrow, thymus, and/or blood. "In T-cell leukemia, MTAP loss is associated with increased tumor aggressiveness and greater risk of tumor transformation to more malignant states." (PMID 41439984, 2025). "The sensitivity of ALA on MTAP-deficient tumors was also apparent in adult T-cell leukemia (ALT)." (PMID 41439984, 2025).
Thoracic Tumours (1 paper, 2025). "Therefore, MTAP immunohistochemistry has been demonstrated to potentially represent a valuable FISH surrogate for the identification of CDKN2A HD in PM,14, 21, 22, 23 as also specified in the 2021 WHO Classification of Thoracic Tumours." (PMID 40566743, 2025).
trypanosomiasis (1 paper, 2017). Infection with protozoa of the genus trypanosoma. "The 5′-methylthioadenosine phosphorylase (MTAP), an enzyme involved in purine and polyamine metabolism and in the methionine salvage pathway, is considered as a potential drug target against cancer and trypanosomiasis." (PMID 29258562, 2017).
cancer (223 papers, 2004 to 2026). A tumor composed of atypical neoplastic, often pleomorphic cells that invade other tissues. "In cancers, a complete loss of MTAP expression (MTAP deficiency) was seen in 33 (0.3 %) of informative samples, while the MTAP staining was considered 1+ in 14.8 %, 2+ in 42.2 %, and 3+ in 42.7 % of tumors." (PMID 40554389, 2025). "Immune checkpoint inhibitors (ICIs) have transformed cancer therapy; however, their efficacy remains limited in certain tumor subtypes, including those deficient in methylthioadenosine phosphorylase (MTAP)." (PMID 41246302, 2025). "We previously demonstrated that MTAP functions as a metastasis suppressor, and that MTAP-deficient cancer cells reprogram immune-related pathways and cytokine profiles, contributing to the establishment of an immunosuppressive “cold” TME." (PMID 41246302, 2025). "CB-839 was evaluated across four matched pairs of MTAP-expressing and MTAP-deficient cancer cell lines." (PMID 41246302, 2025). "MTAP loss is well studied in cancer 85, but its role in vascular pathophysiology has been largely unexplored." (PMID 41332607, 2025). "The reversal of all these expectable MTAP associations with tumor phenotype and patient outcome in cancers carrying an TMPRSS2:ERG fusion is the most striking finding of this study." (PMID 40554389, 2025). "MTAP-deficient cancers are characterized by immunosuppressive tumor microenvironments (TMEs) and poor T cell infiltration, as suggested by large-scale transcriptomic analyses." (PMID 41246302, 2025). "In 13,189 interpretable cancers, a complete loss of MTAP staining was seen in 33 (0.3 %) tumors, while MTAP staining was considered 1+ in 14.8 %, 2+ in 42.2 %, and 3+ in 42.7 % of tumors." (PMID 40554389, 2025). "It must be expected that tumors with heterogeneous MTAP deficiency will be much less responsive to respective therapies than cancers with MTAP deficiency in all cancer cells." (PMID 40227771, 2025). "Loss of MTAP results in the accumulation of methylthioadenosine (MTA) in cancer cells, that partially inhibits the PRMT5 methyltransferase activity." (PMID 40157258, 2025). "Transcriptomic analyses revealed that MTAP-deficient cancer cells reprogram immune signaling pathways and suppress the expression of CXCL10, a key chemokine for T cell recruitment, thereby contributing to a non-inflamed, “cold” TME." (PMID 41246302, 2025). "In ERG positive cancers, low MTAP expression was associated with deletions of PTEN (p = 0.0002), 12p13 (p < 0.0001), and 18q21 (p = 0.0006)." (PMID 40554389, 2025). "Although varied amoung cancers, more than 80% of MTAP-loss cancers also display codeletion of CDKN2A." (PMID 41583489, 2025). "MTAP deficiency results in a critical vulnerability of cancer cells towards drugs targeting different pathways." (PMID 40664803, 2025). "MTAP-deficient cancer cells showed impaired induction of key chemokines, CXCL9, CXCL10, and CXCL11, particularly in response to immune cell interaction, thereby contributing to the development of an immunosuppressive “cold” tumor microenvironment." (PMID 41246302, 2025). "MTAP deficiency was found in almost 40% of all cancers, was always caused by homozygous deletion, and was rarely heterogenous in TMA and large-section analyses (less than 10%)." (PMID 40227771, 2025). "Having uncovered the mechanistic role of MTAP deficiency in promoting immune evasion, we next sought to identify therapeutic strategies that selectively target MTAP-deficient cancer cells while potentially enhancing antitumor immune responses." (PMID 41246302, 2025). "The gene encodingfor MTAP is one of the most commonly deletedgenes in cancer, occurring in approximately 10–15% of all humancancer." (PMID 40035511, 2025). "The cancer with heterogeneous MTAP status contained large areas of both MTAP-deficient and MTAP-proficient adenocarcinoma." (PMID 40227771, 2025).
cancer (continued). "Enhancing the toxicity caused by MTA in homozygous MTAP-deleted cells through molecularly targeted therapies can lead to the effective elimination of cancer cells." (PMID 41465382, 2025). "This review summarizes current knowledge on the biological functions of MTAP, the mechanisms linking its loss to oncogenesis, and the evolving landscape of therapeutic strategies targeting MTAP-deficient cancers." (PMID 41465382, 2025). "The OS of patients with complete MTAP expression loss in pT2–4 cancers was worse than for patients with retained MTAP expression (p = 0.0103)." (PMID 39668577, 2025). "Studies in malignant mesothelioma, a cancer that often shows homozygous 9p21 deletions, have shown that MTAP IHC can serve as a diagnostic tool for the distinction of malignant from benign mesothelial proliferations." (PMID 39668577, 2025). "This creates a metabolic vulnerability in MTAP-deficient cancers, as the inhibition of PRMT5 is more sensitized than normal cells for disrupting essential methylation-dependent processes required for cell survival." (PMID 39826691, 2025). "Our findings support further evaluation of glutaminase inhibition, particularly CB-839, as a means to restore antitumor immunity in MTAP-deficient cancers and to enhance the efficacy of immune checkpoint blockade in tumors that are otherwise resistant." (PMID 41246302, 2025). "MTAP is a versatile biomarker for targeted therapies in cancers with 9p21 loss, given its prominent role in regulating the metabolic, immune, and proliferative states of multiple tumors." (PMID 41439984, 2025). "To further understand the regulatory mechanisms underlying glutamate dependency in MTAP-deficient cancer cells, we examined the expression of glutaminase 1 (GLS1), the target of CB-839, and key glutamine/glutamate transporters." (PMID 41246302, 2025). "The gene encoding S-methyl-5′-thioadenosine phosphorylase (MTAP), a key enzyme in the methionine salvage pathway, is frequently deleted in cancers due to its proximity to the p16/ARF tumor suppressor locus." (PMID 39862967, 2025). "• CD39+ and CD73+ EVs.• Spread of EVs to TDLN and metastatic sites.• IL-2 is available to both CD8 and Treg for their expansion.• MTAP loss variant cancers bypass direct A2AR antagonist blocking." (PMID 41583489, 2025). "This thesis has informed the development of innovative small-molecule drugs, which are being tested in clinical trials in patients with various types of cancer with MTAP loss." (PMID 41465382, 2025). "Loss of MTAP has been associated with enhanced cancer cell stemness in GBM as demonstrated by increased expression of prominin-1 (PROM1), also known as CD133, further elevating the tumorigenicity of these cells." (PMID 41439984, 2025). "By identifying the frequency of MTAP homozygous deletion and low mRNA expression, clinical trials can be designed for specific cancers that show prominence in MTAP loss." (PMID 41439984, 2025). "Complete expression loss of S-methyl-5′-thioadenosine phosphorylase (MTAP) is caused by homozygous 9p21 deletion and results in a critical vulnerability of cancer cells towards drugs targeting multiple different pathways." (PMID 40664803, 2025). "Another consideration is how METTL16 cancer-associated mutants participate in methylation-independent functions and/or alterations in other genes, such as MTAP." (PMID 41007290, 2025). "In a recent example, the MTA-cooperative PRMT5 inhibitor, AZ-PRMT5i-1, has shown potent inhibitory effects on specific cancer cell lines, particularly those with MTAP deficiency." (PMID 39826691, 2025). "Together, these findings demonstrate that MTAP-deficient cancer cells display a critical dependence on glutamate metabolism." (PMID 41246302, 2025). "The high MTA and low SAM environments diminish PRMT5 function and activity in MTAP-deficient cancers." (PMID 40430461, 2025).
cancer (continued). "Accordingly, the loss of MTAP in cancer cells exposes several collateral vulnerabilities in the SAM-PRMT5 pathway, including MAT2A and PRMT518,19." (PMID 41339334, 2025). "MTA-cooperative PRMT5 inhibitors are designed to selectively target the PRMT5 form in MTAP-deficient cancer cells by enhancing the natural inhibitory effect of accumulated MTA, sparing normal tissues." (PMID 39826691, 2025). "In multivariate analyses including pT and pN, both MTAP loss (p = 0.0062) and 9p21 deletions (p = 0.0407) were independent predictors of prognosis in pT2–4 cancers." (PMID 39668577, 2025). "MTAP deficiency frequently occurs in cancers due to its codeletion with the tumor suppressor gene CDKN2A." (PMID 39826691, 2025). "Inhibition of PRMT5 in MTAP-deficient cancers offers a promising strategy to exploit this synthetic lethality, potentially improving outcomes in tumors harboring this common genomic alteration." (PMID 39826691, 2025). "The deleted form of the MTAP gene occurs in approximately 15% of cancers and has been linked to immune evasion." (PMID 40519286, 2025). "Prior studies showed that type I PRMT and type II PRMT5 inhibitors are effective specifically in MTAP-deficient cells; yet, our data in MTAP-intact cancer cells show that targeting PRMT1 reduces persistence." (PMID 39699269, 2025). "There is added credence to MAT2A as a bona fide drug target, as inhibitors of MAT2A are being investigated in Phase I clinical trials for tumors with loss of the gene MTAP, constituting 15% of cancers." (PMID 40880532, 2025). "Loss of MTAP has been reported by multiple studies spanning different cancer types, including through the utilization of the PCAWG Consort." (PMID 41439984, 2025). "This inhibitor shows promise as a targeted therapy for MTAP-deficient cancers, including nonsmall cell lung cancer, mesothelioma, and pancreatic cancer, with early signs of clinical efficacy in these cancer types." (PMID 39826691, 2025). "MAT2A inhibitors efficiently suppress the activity of MAT2A, leading to a substantial decline in SAM levels and exhibiting robust anti-proliferative effects through synthetic lethality in MTAP-deficient cancer cells." (PMID 40430461, 2025). "Deficiency of MTAP leads to critical cancer cell vulnerability towards drugs targeting several different pathways." (PMID 40227771, 2025). "Among 41 consecutive pT2-4 carcinomas from which 1–15 (average 6.4) whole sections were analyzed, MTAP was homogeneously deficient in 34.1%, heterogeneously deficient in 4.9% and homogeneously retained in 61.0%." (PMID 40664803, 2025). "MTAP loss was linked to advanced stage and poor overall survival in pT2–4 carcinomas (p < 0.05 each)." (PMID 39668577, 2025). "MAT2A was found as a synthetic lethal target in methylthioadenosine phosphorylase (MTAP)‐deficient cancer cells, and the mechanism involves SAM‐utilizing protein arginine methyltransferase 5 (PRMT5)." (PMID 39309689, 2024). "One of the most common sporadic homozygous deletions in cancers is 9p21 loss, which includes the genes methylthioadenosine phosphorylase (MTAP), CDKN2A, and CDKN2B, and has been correlated with worsened outcomes and immunotherapy resistance." (PMID 38330461, 2024). "Within this complex pathway, loss of the MTAP enzyme compromises cellular vulnerability, rendering cancer cells susceptible to targeted interventions." (PMID 39001391, 2024). "Publications examining the genomic landscape and clinical impact of MTAP-loss are currently limited to the pan-cancer setting, with limited individual sample sizes in GI cancers." (PMID 38330461, 2024). "The purpose of this study is to describe the prevalence of MTAP-loss in GI cancers and examine differences in coalterations between MTAP-loss and MTAP-intact cancers." (PMID 38330461, 2024).